IFFO1 (intermediate filament family orphan 1)
Description:
Nuclear matrix protein involved in the immobilization of broken DNA ends and the suppression of chromosome translocation during DNA double-strand breaks (DSBs). Interacts with the nuclear lamina component LMNA, resulting in the formation of a nucleoskeleton that relocalizes to the DSB sites in a XRCC4-dependent manner and promotes the immobilization of the broken ends, thereby preventing chromosome translocation. Acts as a scaffold that allows the DNA repair protein XRCC4 and LMNA to assemble into a complex at the DSB sites.
Synonyms: IFFO; HOM-TES-103
Tractability: PROTAC: ubiquitination databases record sites on it.
Gene: Protein-coding gene on chromosome 12 (6,538,961 to 6,556,102, reverse strand). Ensembl gene ENSG00000010295.
Subcellular location: Nucleus; Nucleus, nucleoplasm; Nucleus inner membrane; Nucleus matrix
Gene Ontology:
Molecular function: cytoskeletal anchor activity; protein binding
Biological process: DNA double-strand break attachment to nuclear envelope; double-strand break repair via nonhomologous end joining; protein localization to site of double-strand break
Cellular component: nuclear inner membrane; nuclear matrix; nucleoplasm; nucleus; site of double-strand break
Genetic constraint (gnomAD): Loss-of-function variants: 42 observed, 59.68 expected, observed/expected ratio (o/e) 0.7, 90% interval 0.55 to 0.91. The upper end of that interval is the gene's LOEUF score, 0.91, which puts it in group 3 of 6, group 1 being the genes least tolerant of losing a copy. Missense variants: 711 observed, 797.39 expected, observed/expected ratio (o/e) 0.89, 90% interval 0.84 to 0.95. Synonymous variants: 336 observed, 335.63 expected, observed/expected ratio (o/e) 1, 90% interval 0.92 to 1.1.
Homologues: Orthologues: chimpanzee IFFO1 (99% identical), macaque IFFO1 (99% identical), dog IFFO1 (96% identical), pig IFFO1 (95% identical), mouse Iffo1 (93% identical), rat Iffo1 (93% identical), guinea pig IFFO1 (91% identical), zebrafish iffo1a (61% identical), zebrafish iffo1b (59% identical), tropical clawed frog iffo1 (29% identical). Paralogues in human: IFFO2 (53% identical).
Diseases named in the same sentence as IFFO1 in open-access papers:
IFFO1 is named in the same sentence as 17 diseases in open-access papers, as found by Europe PMC text mining. Sharing a sentence is not in itself a finding about the gene and the disease. The quoted sentences say what the papers report.
ovarian carcinoma (11 papers, 2013 to 2025). A malignant neoplasm originating from the surface ovarian epithelium. "Recently, IFFO1 inhibited tumor metastasis and reversed drug resistance through histone deacetylase and RNA methylation mechanisms in ovarian cancer." (PMID 40909968, 2025). "In studies involving ascites and blood samples for ovarian cancer, promoter methylation of the IFFO1 exhibited potential as an effective biomarker." (PMID 40634295, 2025). "In ovarian cancer, intermediate filament family orphan 1 (IFFO1) suppresses tumor metastasis and cisplatin resistance by inhibiting β-catenin nuclear translocation." (PMID 40867514, 2025). "Another example of the involvement of class IIa HDACs in cisplatin resistance in ovarian cancer is the tumor suppressive role of intermediate filament family orphan 1 (IFFO1)." (PMID 39624079, 2024). "It is poorly expressed in ovarian cancer tissue, as well as other cancer tissues, and cisplatin-resistant cells are characterized by a low IFFO1 level." (PMID 39624079, 2024). "The METTL3/YTHDF2 axis can lead to cisplatin resistance of ovarian cancer by regulating the mRNA stability of IFFO1 in an m6A-dependent manner and inhibiting IFFO1 expression." (PMID 37319315, 2023). "In this regard, the recruitment of HDAC5 has been described to modulate the novel tumour suppressor IFFO1 that inhibits tumour metastasis and reverses drug resistance in ovarian cancer." (PMID 37686015, 2023). "An overexpression of HDAC5 in ovarian cancer cells inhibits the transcription of IFFO1 and enhances the proliferation, migration and chemoresistance of ovarian cancer cells." (PMID 37894746, 2023). "IFFO1 is differentially expressed in tumor and control tissues in liver cancer, and is downregulated at both transcriptional and post-transcriptional levels in ovarian cancer with the inhibition of tumor metastasis and reversing drug resistance." (PMID 40634295, 2025). "In ovarian cancer, its promoter was hypermethylated and IFFO1 was proposed as a biomarker." (PMID 31244774, 2019). "Circulating methylated SEPTIN 9 (SEPT9) DNA and INTERMEDIATE FILAMENT FAMILY ORPHAN 1 (IFFO1) DNA in plasma were found to correlate with the occurrence of colorectal cancer and ovarian cancer, respectively." (PMID 23950870, 2013). "In another study on the tumour suppressor IFFO1, researchers found that the METTL3/YTHDF2 axis regulates the mRNA stability of IFFO1 in an m6A-dependent manner, which inhibits metastasis and reverses drug resistance in ovarian cancer cells." (PMID 36894952, 2023).
lung carcinoma (2 papers, 2019 to 2025). "The RNA sequencing (RNA-seq) data from 1041 lung cancer tissues and 108 normal adjacent tissues showed lower IFFO1 expression levels in tumors than in normal tissues." (PMID 40634295, 2025). "Our study revealed that IFFO1 is downregulated in lung cancer patients and is correlated with a poorer prognosis." (PMID 40634295, 2025). "We then determined the expression level of IFFO1 to understand its physiological role in lung cancer patients." (PMID 40634295, 2025). "Considering the significance of IFFO1 in the advancement of lung cancer, a transcriptomic analysis was conducted to explore the underlying mechanisms." (PMID 40634295, 2025). "The Kaplan–Meier survival curve indicated a positive correlation between IFFO1 expression and the overall survival in lung cancer patients." (PMID 40634295, 2025). "The result indicated a reduced expression of IFFO1 in lung cancer cell lines compared to human embryonic lung fibroblast cell line MRC-5." (PMID 40634295, 2025). "Our results indicated that IFFO1 was downregulated in lung cancer and its subtypes, and this downregulation was strongly correlated with tumor progression and recurrence." (PMID 40634295, 2025). "In our study, we comprehensively investigated the significance of IFFO1, whose function remains unelucidated in lung cancer, with a specific focus on the interaction domains that regulate tumor progression." (PMID 40634295, 2025). "The IFFO1 expression level was lower in the two subtypes of lung cancer (lung adenocarcinoma and lung squamous cell carcinoma) than in normal tissues." (PMID 40634295, 2025). "Our study demonstrates the multifaceted roles of IFFO1 in lung cancer by modulating the IQGAP3-Cdc42 axis and suggests the potential for identifying tumor targets through the examination of intermediate filament networks and their associated co-factors." (PMID 40634295, 2025). "Transwell assay was performed to assess the role of IFFO1 in lung cancer cell migration." (PMID 40634295, 2025). "Thus, the low expression of IFFO1 in lung cancer promoted cell migration and movement, which might be due to an enhancement of N-cadherin, Vimentin, and Cdc42 expression levels." (PMID 40634295, 2025). "Our findings indicated that IFFO1 did not exert a significant effect on active Ras in two distinct lung cancer cell lines." (PMID 40634295, 2025).
melanoma (2 papers, 2025). A malignant, usually aggressive tumor composed of atypical, neoplastic melanocytes. "In our study, it was observed that IFFO1 could have a promoting effect on melanoma cells." (PMID 40909968, 2025). "We identified dozens of melanoma-increased genes uniquely down-regulated by ZDL, including C-type lectin domain containing 11A (CLEC11A), intermediate filament family orphan 1 (IFFO1), and AE binding protein 1 (AEBP1)." (PMID 40141086, 2025). "In GSE46517, IFFO1, ANKRD10, CLPB, TCAP, and POLG2 displayed high expression, but the expression levels of CHMP4A, ZDHHC11, and ANKMY1 were low in the melanoma group." (PMID 40909968, 2025).
ovarian tumor (2 papers, 2011 to 2020). "Compared with normal blood samples, significant hypo-methylation on IFFO1 promoter is a potentially high-sensitive biomarker for ovarian tumor diagnosis." (PMID 32528944, 2020). "We next tested IFFO1 on 15 ovarian tumors of various histological subtypes, 14 of which have also been used in the initial screening step, and found significant levels of DNA methylation (PMR>20) in all the tumors analyzed." (PMID 22163280, 2011).
dementia (1 paper, 2022). Loss of intellectual abilities interfering with an individual's social and occupational functions. "Mediation tests indicated that injury/inflammation levels affected by IFFO1 variants would also affect dementia (p = 9.5 * 10−6)." (PMID 35173266, 2022). "The results suggest that rare variants in IFFO1 affect sensitivity of the neuronal cytoskeleton to damage, resulting in neurodegeneration and potentially dementia symptoms." (PMID 35173266, 2022). "The results suggest that rare variants in IFFO1, DTNB, NLRC3, and SLC22A10 heighten susceptibility to neuronal injury and inflammation, potentially by altering cytoskeleton structure and immune activity disinhibition, resulting in an elevated dementia risk." (PMID 35173266, 2022).
endometrioid endometrial adenocarcinoma (1 paper, 2019). "The hypomethylation and up-regulation of IFFO1 have been also reported in endometrioid endometrial adenocarcinoma samples." (PMID 31244774, 2019).
non-small cell lung carcinoma (1 paper, 2020). A group of at least three distinct histological types of lung cancer, including non-small cell squamous cell carcinoma, adenocarcinoma, and large cell carcinoma. "IFFO1 methylation participates in non-small-cell lung cancer, and PUM1 is an RNA-binding protein gene that participates in multiple biological processes, such as translational regulation and cell development." (PMID 32528944, 2020). "In addition, hyper-methylation of IFFO1 represses its expression in non-small-cell lung cancer." (PMID 32528944, 2020).
tumor (11 papers, 2019 to 2025). "Previous studies have indicated that the expression levels of IFFO1 were associated with tumor progression and immune infiltration." (PMID 40909968, 2025). "The depletion of IFFO1 led to enhanced tumor proliferation both in vitro and in vivo, as well as increased cellular migration, alterations in the cytoskeleton and modifications in GTPase-mediated signal transduction." (PMID 40634295, 2025). "More importantly, IFFO1 expression in the tumor tissues of patients with relapse was significantly lower than that in patients without relapse in the GSE30219 dataset." (PMID 40634295, 2025). "This study indicated that IFFO1 functions not only as an intracellular signaling molecule, but also plays a pivotal role in regulating the mechanisms that govern tumor cell migration through the coordination of protein-protein interactions." (PMID 40634295, 2025). "The IRS score revealed that IFFO1 expression in tissues exhibiting lymph node metastasis was significantly lower compared to that in primary tumor tissues." (PMID 40634295, 2025). "IFFO1−/− cells were subcutaneously implanted in BALB/c nude mice, and the tumor volume of IFFO1−/− cells in transplanted mice was significantly larger than that of wild-type cells." (PMID 40634295, 2025). "The IFFO1 staining in tissue microarray indicated that the alveolar epithelial cells adjacent to the tumor demonstrate elevated levels of IFFO1 expression in comparison to that in tumor tissues." (PMID 40634295, 2025). "The microarray analysis of the GSE18842, GSE19188, and GSE30219 datasets showed downregulation of IFFO1 expression in tumor tissues, and the IFFO1 expression level decreased with the increasing clinical staging." (PMID 40634295, 2025). "IFFO1 is downregulated in OC to confer cisplatin resistance, tumor progression, and metastasis, and overexpressed IFFO1 hinders the β-catenin translocation to nucleus, resulting in reduced metastasis and enhanced sensitivity to cisplatin." (PMID 38544837, 2024). "METTL3‐mediated m6A modification decreases the expression of IFFO1, a novel tumor suppressor, via affecting mRNA stability to promote tumor development and cisplatin resistance in ovarian cancer." (PMID 39006762, 2024). "Histopathological examination of the most extensive region of the lung demonstrated a heightened vascular invasion infiltrating the vascular endothelium in the IFFO1−/− cohort, as well as an augmented presence of small tumor clusters, forming micro-metastatic foci." (PMID 40634295, 2025). "Because of the similarity in structure and function between IFFO1 and Lamin A/C, we speculate that IFFO1 may undergo PTMs during tumor progression." (PMID 40634295, 2025). "IFFO1 plays an important role in the regulation of tumor progression and immune infiltration." (PMID 39624079, 2024). "However, the functional contributions of IFFO1 in tumor progression remain inadequately understood." (PMID 40634295, 2025). "The top gene is IFFO1, which may have a unique expression pattern in eight tumor tissues." (PMID 31456818, 2019).
cancer (4 papers, 2019 to 2023). A tumor composed of atypical neoplastic, often pleomorphic cells that invade other tissues. "IFFO1 was reported to be downregulated by promoter methylation in different cancer types." (PMID 32156068, 2020). "In addition to these, we also identified some novel genes among the 14-CpG markers that were not previously associated with cancer recurrences such as IFFO1, ALKAL1, FAHD1, FSTL4, SLC7A9, IQCJ-SCHIP1, CLDN11 and three other CpGs at intergenic regions." (PMID 34207933, 2021). "Intermediate filament family orphan 1 (IFFO1) can inhibit the nuclear accumulation of β-catenin, cancer metastasis and cisplatin resistance." (PMID 37894746, 2023).
hematological malignancies (1 paper, 2025). "In a previous study, we revealed that IFFO1–Lamin A/C expression negatively correlates with the frequency of gene fusion in multiple carcinoma types, consistent with an increasing range of tumors characterized by down-regulation of A-type lamin expression, including hematological malignancies." (PMID 41359381, 2025).
IFFO1 also shares sentences with these, for which no sentence is quoted: Alzheimer disease (1 paper); colorectal cancer (1); lung adenocarcinoma (1); lung squamous cell carcinoma (1); nervous system tumor (1); Obesity (1); type-2 diabetes (1).